MS4A14 (membrane spanning 4-domains A14)
Description:
May be involved in signal transduction as a component of a multimeric receptor complex.
Synonyms: MS4A16; NYD-SP21; FLJ32856; DKFZp434H092
Tractability: Antibody: UniProt predicts a signal peptide or a membrane-spanning region; its Gene Ontology location is reachable by antibodies, with medium confidence; the Human Protein Atlas places it where antibodies can reach. PROTAC: ubiquitination databases record sites on it.
Gene: Protein-coding gene on chromosome 11 (60,378,530 to 60,417,756, forward strand). Ensembl gene ENSG00000166928.
Subcellular location: Membrane
Subcellular location (Human Protein Atlas): Nucleoplasm; Plasma membrane
Gene Ontology:
Molecular function: protein binding
Biological process: cell surface receptor signaling pathway
Cellular component: plasma membrane; membrane
Genetic constraint (gnomAD): Loss-of-function variants: 12 observed, 12.45 expected, observed/expected ratio (o/e) 0.96, 90% interval 0.62 to 1.55. The upper end of that interval is the gene's LOEUF score, 1.55, which puts it in group 6 of 6, group 1 being the genes least tolerant of losing a copy. Missense variants: 781 observed, 787.36 expected, observed/expected ratio (o/e) 0.99, 90% interval 0.94 to 1.05. Synonymous variants: 294 observed, 294.75 expected, observed/expected ratio (o/e) 1, 90% interval 0.91 to 1.1.
Homologues: Orthologues: macaque MS4A14 (86% identical), chimpanzee MS4A14 (60% identical), dog MS4A14 (49% identical), mouse Ms4a14 (45% identical), rat Ms4a14 (43% identical), zebrafish ms4a17a.17 (7% identical), zebrafish ms4a17a.10 (7% identical), zebrafish si:dkey-77f5.10 (7% identical), zebrafish ms4a17a.11 (7% identical), zebrafish ms4a17a.12 (6% identical), zebrafish ms4a17a.16 (6% identical), zebrafish si:ch73-56d11.5 (6% identical), and 18 more. Paralogues in human: MS4A1 (8% identical), MS4A4A (8% identical), MS4A2 (8% identical), MS4A12 (7% identical), MS4A15 (7% identical), MS4A18 (7% identical), MS4A7 (7% identical), MS4A8 (7% identical), MS4A3 (6% identical), MS4A5 (6% identical), MS4A10 (6% identical), MS4A6A (6% identical), and 4 more.
Diseases named in the same sentence as MS4A14 in open-access papers:
MS4A14 is named in the same sentence as 5 diseases in open-access papers, as found by Europe PMC text mining. Sharing a sentence is not in itself a finding about the gene and the disease. The quoted sentences say what the papers report.
colorectal cancer (1 paper, 2021). A primary or metastatic malignant neoplasm that affects the colon or rectum. "In addition, it has been reported that MS4A14 protein expression was detected in several cases of colorectal cancer, and retained expression was observed during the malignant transformation of tumours." (PMID 34573430, 2021).
epilepsy (1 paper, 2025). A brain disorder characterized by episodes of abnormally increased neuronal discharge resulting in transient episodes of sensory or motor neurological dysfunction, or psychic dysfunction. "Our results revealed a marked upregulation of MS4A4A, MS4A6A, MS4A7, and MS4A14 in lesional tissues of FEAT epilepsy patients relative to perilesional tissues." (PMID 40349168, 2025).
lung adenocarcinoma (1 paper, 2023). A carcinoma that arises from the lung and is characterized by the presence of malignant glandular epithelial cells. "According to the Kaplan-Meier curve, patients with lung adenocarcinoma having poor expression of MS4A2, MS4A7, MS4A14, and MS4A15 had a low overall survival rate." (PMID 37533433, 2023).
tumor (2 papers, 2021 to 2022). "FKBP11, PHF19, ARPC3, and MS4A14 were overexpressed in tumor tissues." (PMID 35651604, 2022).
cancer (1 paper, 2021). A tumor composed of atypical neoplastic, often pleomorphic cells that invade other tissues. "Those 6 genes in the model (PDK4, MPP1, ASGR1, MS4A14, FCER1A and MX2), rarely reported in cancers, were found to be significantly related to the prognostic survival of KIRC patients." (PMID 34606472, 2021).